STAT3 (signal transducer and activator of transcription 3)
Diseases named in the same sentence as STAT3 in open-access papers (continued):
Sharing a sentence is not in itself a finding about the gene and the disease.
breast cancer (continued). "GRN enhances the transcriptional activity of tyrosine-phosphorylated STAT3, and the knockdown of GRN preferentially reduces the viability of breast cancer cells with constitutively active PY-STAT3." (PMID 26000098, 2015). "We tested the effect of a Stat3 inhibitor, WP1066, on breast cancer brain metastasis in a preclinical mouse model." (PMID 25881542, 2015). "Immunoblotting analysis provided a link between ezrin expression and a key angio/lymphangiogenesis signaling pathway by revealing that ezrin regulates Stat3 activation, VEGF-A/-C and IL-6 expression in breast cancer cell lines." (PMID 25231728, 2014). "We have previously identified a specific upregulation of the transcription factor STAT3 from the HER2-overexpressing and ER-positive human breast cancer cell line MCF7-HER2 (unpublished data)." (PMID 24297508, 2014). "YB-1 protects breast cancer cells from apoptosis via activation of AKT/mTOR and phosphorylation of STAT3 at serine 727 and in renal cancer YB1 stabilizes STAT3 and YB-1/STAT3 signaling mediate resistance to interferon a therapy." (PMID 24722453, 2014). "For example, aberrant activity of STAT3, PI3K, NF-κB, MAPK, and Wnt driven cascade is observed in both HCMV infection and breast cancer." (PMID 25202681, 2014). "As a STAT3 inhibitor, JSI124 has been extensively used for the treatment of various types of tumor cells, including those of breast cancer." (PMID 25013518, 2014). "Moreover, MDSCs have been closely related to a lung metastatic in patients with breast cancer.As niclosamide inhibited Stat3 signaling pathway in breast cancer cells, we further investigated whether it also reduced the number of tumor-infiltrating MDSCs (Gr1+ CD11b+)." (PMID 24416452, 2014). "Emerging evidence suggests that STAT3 plays critical roles in maintaining CSCs and promoting EMT in PCa as well as head and neck, hepatocellular carcinoma, glioblastoma and breast cancers." (PMID 24722453, 2014). "We demonstrated that the STAT3 inhibitor, Stattic, treatment abolished the cancer stem cell phenotype in HER2-positive breast cancers." (PMID 24297508, 2014). "Kim and colleagues were the first to demonstrate that overexpression of another dominant-negative STAT3, which inhibits phosphorylation of STAT3 at Tyr705, resulted in radiosensitization of human MDA-MB-231 breast cancer cells." (PMID 25268165, 2014). "Their functions in endocrine-sensitive and resistant breast cancer are still poorly defined and the published literature indicates complex roles, particularly for STAT1 and STAT3." (PMID 24728078, 2014). "In particular, STAT3 and STAT5 are generally thought to mediate opposite effects in mammary carcinoma cells." (PMID 24913037, 2014). "Our lab has shown that STAT3 mediates EGF-induced expression of the repressor Twist in epidermoid and mammary carcinoma cells." (PMID 24743777, 2014). "Signal transducer and activator of transcription 3 (STAT3) has been shown to transcriptionally activate the expression of EMT inducer TWIST1, resulting in promoted oncogenic properties in breast cancer." (PMID 23819113, 2013). "We examined STAT3 activation in ALDH+ and ALDH+/CD44+/CD24− subpopulations of breast cancer cells by sorting with flow cytometer." (PMID 24376586, 2013). "We observed that STAT3 ShRNA down regulated STAT3 expression and phosphorylation, and induced the cleavage of caspase-3 in ALDH+ breast cancer cells." (PMID 24376586, 2013). "Here we demonstrate that STAT3 physically interacts with CD44 and NF-kB and activates the catalytic subunit of telomerase (hTERT) in human breast cancer stem cells." (PMID 24386318, 2013). "STAT3 inhibitors Stattic and LLL12 inhibited STAT3 phosphorylation, reduced the ALDH+ subpopulation, inhibited breast cancer stem-like cell viability, and retarded tumorisphere-forming capacity in vitro." (PMID 24376586, 2013).
breast cancer (continued). "We previously reported that activated STAT3 promoted epithelial-mesenchymal transition (EMT) and cancer stem cell phenotype in human breast cancer." (PMID 24386318, 2013). "For example, in breast cancer, ERK5 expression is up-regulated by constitutive activation of signal transducer and activator of transcription 3 (STAT3)." (PMID 24239623, 2013). "The JAK2/STAT3 signaling pathway is preferentially activated in CD44+ breast cancer stem cell population over other cell populations, and hyaluronic acid synthase 1 (HAS1) is a STAT3 signaling-related molecule in basal-like breast cancer." (PMID 23326564, 2013). "There was a significant correlation between the nuclear staining of phosphorylated STAT3 and the expression of ALDH1 in breast cancer tissues." (PMID 24376586, 2013). "Specifically, breast cancer stem cells are modulated by signal transduction pathways including the Wnt and IL-6/JAK2/STAT3 pathway." (PMID 24392029, 2013). "In breast cancer cells, PRL activates Jak2, stimulates phosphorylation of Stat1, Stat3 and Stat5 and induces cell proliferation." (PMID 23317095, 2013). "Our results showed that LLL12 is potent in inhibiting STAT3 phosphorylation, cell viability, the formation of tumorspheres, and inducing apoptosis in the ALDH+ subpopulation of breast cancer cells." (PMID 24376586, 2013). "Jak1 was reported to be activated by PRL signaling in human breast cancer lines and cooperate with Jak2 to enhance signaling pathways downstream of PRL receptors, including Stat5, Stat3 and Erk activation." (PMID 23758962, 2013). "Our data suggest that STAT3 is the linking molecule that connects CD44 and NF-kB signaling in aggressive breast cancer cell lines." (PMID 24386318, 2013). "In summary, this study demonstrates that STAT3 is activated in ALDH+ and ALDH+/CD44+/CD24− breast cancer cells." (PMID 24376586, 2013). "To confirm the inhibition of STAT3, we examined the effects of LLL12 on STAT3 phosphorylation in three independent breast cancer cell lines." (PMID 24376586, 2013). "Although stattic can also inhibit cell viability and the formation of tumorspheres in the ALDH+ subpopulation of breast cancer cells it is less potent than LLL12, an observation which is consistent with weaker predictive binding affinity to STAT3 than LLL12." (PMID 24376586, 2013). "We have illustrated here that STAT3 phosphorylation up-regulated hTERT then, activated hTERT enhanced cancer stem cell marker CD44 expression in breast cancer." (PMID 24386318, 2013). "In agreement with our findings, STAT3 is a transcriptional regulator that shows increased activity in solid tumors such as HCC and breast cancers, among others." (PMID 23555719, 2013). "It inhibits STAT3 dimerization, STAT3 nuclear translocation, STAT3 DNA binding, and STAT3-dependent luciferase activity in MDA-MB-435s breast cancer cells." (PMID 24199193, 2013). "The predominant form, PL2L60, is mainly expressed in tumor cells and promotes cell survival and proliferation of a human breast cancer cell line (MDA-MB-231), possibly by the upregulation of Bcl2 and Stat3." (PMID 22748119, 2012). "Anti-angiogenic studies of MSM in human breast cancer cells were mainly focused on VEGF and its regulator STAT3." (PMID 22485142, 2012). "Signal transducer and activator of transcription 3 (STAT3) is an oncogenic transcription factor involved in the development and progression of various malignancies, including breast cancer." (PMID 22792362, 2012). "Thus, STAT3 may promote the progression of breast cancer through the regulation on MMP-9." (PMID 22179587, 2012). "EETs can also activate STAT3 in human breast cancer cell lines, with 14,15-EET promoting STAT3 tyrosine-705 phosphorylation and nuclear translocation." (PMID 22848834, 2012). "We found that HSE can block angiogenesis by modulating the STAT3/VEGF pathway and VEGF-R2 level in human breast cancer cells." (PMID 22792362, 2012).
breast cancer (continued). "Recently, two studies showed that PTPMeg2 promotes dephosphorylation of EGFR and ErbB2 thereafter to impair the activation of STAT3 and STAT5 in breast cancer cells." (PMID 22394684, 2012). "In order to characterize the relationship between activated Stat3 and ATX, we examined a number of breast cancer derived cell lines for expression of ATX message and protein relative to pStat3." (PMID 22140473, 2011). "It has been shown that treatment with 30 μmol/L of S3I-201 for 48 hrs induces significant apoptosis in human breast cancer cell line MDA-MB-435, which harbors constitutive active STAT3." (PMID 21679466, 2011). "Stat3 activation was an absolute requirement in HRG-induced mammary tumor growth, and targeting Stat3 effectively inhibited growth of breast cancer cells with activated HRG/HER2 and PR." (PMID 22295219, 2011). "Our results show that Stat3 and LAP2 (C/EBP-β2) are the two major transcription factors that contribute to Jab1 overexpression that leads to increased proliferation of breast cancer cells." (PMID 21689417, 2011). "Taken together, high level TLR2 expressed in metastatic human breast cancer cells and mediated a bacterial component, PGN, to stimulate NF-κB activity resulting in STAT3 and Smad3 sequential activation, which contributed to invasiveness and adhesiveness." (PMID 20520770, 2010). "In breast cancer (DCIS), both oncostatin M (OSM) and interleukin-6 (IL-6) have been proposed to regulate the expression and activity of S100A7 by regulating PI3K, STAT3 and Erk signaling." (PMID 20689826, 2010). "The peptidoglycan of Staphylococcus aureus (PGN-SA) triggered breast cancer cell TLR2 with NF-κB, STAT3 and Smad3 activation contributing to the cancer cell invasiveness and adhesiveness." (PMID 20520770, 2010). "We have demonstrated that STAT3 and AP-1 are important transcriptional regulators of MMP-7 and MMP-9 in human breast cancer cells previously and STAT3 and AP-1 exert transcriptional regulation functions by binding to their respective elements." (PMID 20939893, 2010). "It is conceivable that BST2 is an important regulator in the STAT3/BST2/IL6 pathway leading to increased cell proliferation, as well as osteoclastic bone destruction and/or production in the bone metastatic breast cancer." (PMID 19338666, 2009). "Our results show that LLL-3 inhibits STAT3-specific DNA binding activity in U373 glioblastoma cells and MDA-MB-231 breast cancer cells as well as inhibits STAT3-dependent transcription activity in luciferase assays in MDA-MB-231 breast cancer cells." (PMID 19127268, 2009). "The results shown here suggest that in well-to-moderately differentiated mammary tumor cells, LIF-induced Stat3 activation preserves the pro-apoptotic role of this factor in non-tumorigenic mammary cells." (PMID 17925034, 2007). "We first compared the phosphorylation profiles of 10 protein kinases and two transcription factors (Stat3 and c-Jun) between normal primary HMEC, TERT, and two breast cancer cell lines, noninvasive MCF-7 and invasive MDA-MB-468." (PMID 16288304, 2005). "To further confirm our investigation on increased phosphorylation in breast cancers, we have applied IHC staining on breast tumours fixed on TMA slides to examine the phosphorylation status of PDK-1, AKT, mTOR, p70S6K, S6, Stat3, and EGFR." (PMID 16288304, 2005). "This is the first report demonstrating phosphorylation of PDK-1 is frequently elevated in breast cancer with concomitantly increased phosphorylation of downstream kinases, including AKT, mTOR, p70S6K, S6, and Stat3." (PMID 16288304, 2005). "Therefore, we collected lung metastasis tissues from four patients with breast cancer within the UPTIDER rapid autopsy program 28 and determined DHHC20 protein expression, STAT3 phosphorylation and KAT2A protein expression." (PMID 41826695, 2026).
breast cancer (continued). "In line, Stat3 silencing abrogated palmitate-induced KAT2A gene and protein expression and spheroid growth in 4T1, and human MCF7, HCC70 and MCF10A H-RasV12 breast cancer cells." (PMID 41826695, 2026). "IL-6 activated STAT3-driven metastasis by co-opting ER-FOXA1-STAT3 enhancers metastasis, suggesting that targeting IL6/STAT3 may have clinical potential in ER+ breast cancer." (PMID 40906676, 2025). "In our study, the depletion of SNRPE might induce ROS generation by inhibiting STAT3, as the knockdown of SNRPE decreased STAT3 level and increased production of ROS in breast cancer cells." (PMID 40386046, 2025). "Although this warrants further study, this could provide helpful information to understand the interplay between STAT3 and STAT5 in breast cancer." (PMID 40507264, 2025). "Therefore, our findings, along with new studies focusing on APE1 and STAT3, could support identifying new promising pharmacological inhibitors for these proteins and contribute to the development of enhanced therapeutic strategies against cancer, including breast cancer." (PMID 41090323, 2025). "Besides, SSA can downregulate the expression of p-STAT3 and p-AKT in breast cancer cells, reduce cellular lactate levels, ATP content, and glucose uptake, and attenuate glycolysis in breast cancer cells." (PMID 39995416, 2025). "The second is JAK/STAT3 signaling, which was shown to regulate CPT1 in breast cancer cells." (PMID 40002245, 2025). "Overall, these observations suggest that, in breast cancers, STAT3 inhibition is not sufficient to explain NIF effect on CSC." (PMID 40038300, 2025). "Our previous studies have shown that imipramine reduces the activity of AKT, extracellular signal‐regulated kinase (ERK), signal transducer and activator of transcription 3 (STAT3) and nuclear factor‐kappaB (NF‐κB), thereby interfering with the progression of lung, oral and breast cancers." (PMID 40889216, 2025). "In breast cancer cells, PTPN9 directly dephosphorylates EGFR and ErbB2, attenuating downstream STAT3/STAT5 signaling, suggesting that PTPN9 status could influence responses to EGFR-directed TKIs." (PMID 41275311, 2025). "To explore the differences in STAT3 between different types of breast cancer, we chose to analyze TNBC and non-TNBC samples in the GEO database (GSE76275) using R packages." (PMID 40076902, 2025). "In addition, in breast cancer, PYK2 activates STAT3 (Y705 site), forming “PYK2→STAT3→PYK2” positive feedback." (PMID 40746536, 2025). "Preclinical evidence from related Vaccinium species suggests VAC's translational potential: V. macrocarpon (cranberry) reduced DMBA‐induced mammary tumors by 73% (tamoxifen 55%); V. myrtillus (bilberry) inhibited 4T1 lung metastasis by 82% in BALB/c mice through suppression of IL‐6/STAT3 signaling." (PMID 41234608, 2025). "These cytokines may promote mammary tumorigenesis through activating STAT3 and NF-κB signaling pathways suggesting a potential link between DDT/DDE exposure and breast cancer development." (PMID 40034592, 2025). "The pro-oncogenic transcription factor STAT3 forms a positive feedback loop with some of the inflammatory cytokines, including IL-6, and promotes MMP13 expression in murine breast cancer CAFs; furthermore, MMP13 plays an important role in maintaining the function of CAFs." (PMID 40243781, 2025). "This review aims to summarize the recent discoveries regarding the roles that both STAT3 and STAT5 play in breast cancer, specifically focusing on their transcriptional functions, the cofactors involved in regulating their transcriptional activity, and their direct relationship with each other." (PMID 40507264, 2025). "It is also reported that direct binding of STAT3 with CD44 and NF-kB increases CD44 expression via human telomerase reverse transcriptase-mediated autocrine signaling in the breast cancer cell lines, which can contribute to promote a cancer stem cell phenotype." (PMID 40021617, 2025).
breast cancer (continued). "Although the complete role of STAT3 in breast cancer has not yet been fully elucidated, these studies provide evidence that STAT3 can be targeted to reduce proliferation and promote breast cancer cell death." (PMID 40507264, 2025). "Importantly, another STAT3 inhibitor, TTI-101, has also been studied in a clinical trial addressing many cancer types, including breast cancer (NCT03195699), suggesting its potential as a therapeutic target." (PMID 40507264, 2025). "The hub targets identified for SRC, PIK3R1, PIK3CA, STAT3, and EGFR may represent significant therapeutic targets for the treatment of breast cancer using TSAC." (PMID 40864816, 2025). "However, epigenetic modifications need to be further studied to fully understand their impact on STAT3 and STAT5 transcriptional activity and competition, particularly in the context of competition for BCL6 in breast cancer." (PMID 40507264, 2025). "Additionally, hormone receptor-positive MCF-7 breast cancer cells overexpressing HER2 had higher rates of apoptosis with a combination treatment of Herceptin and the STAT3 inhibitor Stattic, compared to either treatment alone." (PMID 40507264, 2025). "Both STAT3 and STAT5 have been found to be inappropriately activated in breast cancer." (PMID 40507264, 2025). "Simultaneous STAT3 overexpression and ERRα knockdown increased E-cadherin and decreased mesenchymal markers, indicating that ERRα is an important STAT3 target for the promotion of EMT in breast cancer." (PMID 40507264, 2025). "GO‐Y030 inhibits signalling pathways such as IKKβ, STAT3, and AKT, which are crucial for the proliferation and survival of multiple myeloma RPMI8226, KMS12‐BM, and OPM2 cell lines, breast cancer MDA‐MB‐231 cell line, and pancreatic carcinoma PANC‐1, HPAC, and BXPC‐3 cell lines." (PMID 39945243, 2025). "PDP1 gene is overexpressed in breast cancer tissues and correlates with poor prognosis, Validation through in vivo and in vitro experiments further confirmed that PDP1 contributes to cancer progression by regulating STAT3 phosphorylation levels." (PMID 40746885, 2025). "Similarly, CCL18, a TAM-secreted chemokine, activates JAK2/STAT3 signaling in ESCA, correlating with poor prognosis, as seen in ovarian and breast cancers." (PMID 40134607, 2025). "Similarly, BP‐1–102 targets the STAT3 SH2 domain, effectively suppressing cell survival, growth, migration, and invasion in lung and breast cancer." (PMID 40166646, 2025). "Moreover, correlation analysis of the Clinical Proteomic Tumor Analysis Consortium (CPTAC) breast cancer proteome further supported the correlation between the PRL2 protein and STAT3 phosphorylation at Tyr705 in TCGA breast cancer patient samples." (PMID 39665584, 2025). "Moreover, DAB-2-28 inhibits the phosphorylation of key pro-EMT transcriptional factors, such as NFκB, STAT3, SMAD2, CREB, and/or AKT proteins, in breast cancer cells exposed to different EMT inducers." (PMID 40807456, 2025). "Furthermore, CAFs activate numerous signaling pathways, including JAK/STAT3, PI3K/Akt, and NF-κB, to promote trastuzumab resistance in HER2-positive breast cancer cells." (PMID 40843360, 2025). "Indeed, DDR1i caused differential expression in several direct RUNX1 target genes including DUT, an essential nucleotide metabolism enzyme seen upregulated across breast cancers, and MYC, along with ANP32B, PLEC, CEBPD, ID1, and STAT3." (PMID 40614729, 2025). "Previously, we have reported that in inflammatory carcinogenesis and obesity-mediated breast cancer, S1P exacerbates cancer progression through a positive-feedback mechanism mediated by S1PR1 and Stat3 and that FTY720 inhibits tumor growth by blocking this pathway." (PMID 40528704, 2025). "In bone metastases of breast cancer, LIFR knockdown disrupts the dormancy phenotype, with STAT3 being an essential factor in LIFR signaling, and LIF upholds the dormancy phenotype through the LIFR: STAT3: SOCS3 pathway." (PMID 40977686, 2025).